SFXN1 (sideroflexin 1)
Diseases named in the same sentence as SFXN1 in open-access papers (continued):
Sharing a sentence is not in itself a finding about the gene and the disease.
tumor (continued). "Additionally, SFXN1 expression correlated with the expression of multiple immunomodulators, which act to regulate the tumor immune microenvironment." (PMID 38233752, 2024). "Immunohistochemical analysis of the grafted tumors confirmed a decrease in SFXN1 protein expression in the SFXN1-KO tumor tissues, and revealed that the Ki-67 labeling index was markedly lower in tumor specimens of the Control-HFD group in comparison to the other three groups." (PMID 37296228, 2023). "SFXN1 appears to be functionally linked with cell survival and growth promotion genes (AKT1, BCL2, MTOR) and pro-apoptotic components (BAX, CASP3), indicating its dual role in maintaining mitochondrial homeostasis and regulating cell fate decisions in tumor cells." (PMID 41399448, 2026). "While SFXN1 expression was associated with tumor grade and nodal involvement, no significant stage-specific differences were observed (F = 0.879, p = 0.452), indicating that SFXN1 overexpression occurs regardless of tumor stage rather than being correlated with disease progression." (PMID 41399448, 2026). "Importantly, our study found that a large number of MCs, eosinophils, macrophages, MDSCs, and Treg cells infiltrated the SFXN1 high-expression group, all of which can shape an immunosuppressive microenvironment and promote tumor growth under certain conditions." (PMID 38233752, 2024). "Thus, inhibiting the expression of SFXN1, which is the key transporter of serine into mitochondria, may reduce tumor development." (PMID 38233752, 2024). "Therefore, SFXN1 may modulate the tumor immune microenvironment by directly or indirectly influencing the infiltration of immune cells." (PMID 38233752, 2024). "Therefore, SFXN1 and its homologous proteins may be an important node regulating the fate of serine in cells and may also play an important role in tumor cell growth." (PMID 36138824, 2022). "Bioinformatic analyses demonstrated that SFXN1 is significantly overexpressed in OSCC and is positively correlated with advanced clinical features such as tumor grade and nodal metastasis." (PMID 41399448, 2026). "SFXN1 is frequently upregulated in LUAD and has a significant impact on the tumor immune environment." (PMID 38233752, 2024). "This study shows that high-fat diet feeding reduces tumor growth of HCC cells, suggesting the latter mechanism, and that SFXN1 knockout attenuates lipid accumulation in vitro and mitigates lipotoxicity in vivo." (PMID 37296228, 2023). "SFXN1 is positioned centrally in the PPI network and plays a dual role in tumor progression." (PMID 41399448, 2026). "SFXN1 drives malignant tumor progression via canonical (metabolic) and noncanonical (non-metabolic) pathways." (PMID 41415540, 2025). "Although studies of SFXN members mainly focused on SFXN1, it is appealing that SFXN4 implicated in both tumor and non-tumor diseases." (PMID 37786439, 2023).
cancer (10 papers, 2020 to 2026). A tumor composed of atypical neoplastic, often pleomorphic cells that invade other tissues. "The circular Cytoscape network map, which places SFXN1 at the core, reflects its high connectivity and potential regulatory influence on numerous cancer-associated genes." (PMID 41399448, 2026). "Various SFXN1 expression groups showed significant enrichment of pathways, with SFXN1 exhibiting somatic gene mutations in cancer-related signaling pathways like RTK-RAS, WNT, NOTCH, Hippo and PI3K which indicates its critical role in cancer development." (PMID 38233752, 2024). "Transcriptomic data from TCGA pan-cancer cohorts were analyzed to evaluate SFXN1 expression patterns." (PMID 41399448, 2026). "Our findings provide insights into the role of SFXN1 in cancer biology through pathway analysis and functional validation." (PMID 41399448, 2026). "We utilized data from the TCGA database to assess SFXN1 expression across cancers, specifically in HNSC, which is closely related to OSCC." (PMID 41399448, 2026). "Our findings provide insights into the role of SFXN1 in cancer biology through pathway analysis and functional validation, although several methodological limitations must be acknowledged." (PMID 41399448, 2026). "Moreover, an analysis of the association between SFXN1 and clinicopathologic characteristics, overall survival status, drug sensitivity, and immune cell infiltration demonstrated that SFXN1 plays a pivotal role in both cancer development and regulation of the immune microenvironment." (PMID 38233752, 2024). "Lastly, we assessed the potential prognostic value of SFXN1 expression in a range of cancer types within the TCGA database." (PMID 38233752, 2024). "Recently, Nora Kory and colleagues verified that SFXN1 serves as a mitochondrial serine transporter in the process of one-carbon metabolism and is highly expressed in many cancers." (PMID 38233752, 2024). "Compared with paracancerous tissues, the mRNA expression of SFXN1 is significantly increased in cancer tissues, and SFXN1 promotes the progression of NSCLC by activating the mTOR signaling pathway." (PMID 36902385, 2023). "One-carbon metabolism also generates purine synthesis which contributes to proliferation of cancer cells, and SFXN1 has been found to be expressed in many cancers." (PMID 34350187, 2021). "Strategies targeting SFXN1 could offer novel avenues for therapeutic intervention, warranting further investigation in clinical and translational cancer research." (PMID 41399448, 2026). "Given the importance of metabolic reprogramming in cancer progression and the emerging involvement of SFXN1 in malignancies, we hypothesized that SFXN1 might play a crucial role in OSCC." (PMID 41399448, 2026). "Because a crowd of malignancies depends on the one-carbon units produced from serine for rapid proliferation and SFXN1 is expressed in many cancers, SFXN1 may play a special role in the proliferation of cancer." (PMID 33489900, 2020). "Thus, SFXN1 may exacerbate LUAD progression by promoting cancer cell proliferation, inhibiting apoptosis, and activating invasion and metastasis pathways." (PMID 38233752, 2024). "Pathway analysis highlighted the connection of SFXN1 to key signaling cascades, including the mTOR, PI3K-Akt, and HIF-1 pathways, which are pivotal in cancer progression, metabolism, and the hypoxia response." (PMID 41399448, 2026). "It is unknown whether SFXN1 and BAIAP2L2 are involved in the cancer process as few studies on these two genes have been reported." (PMID 32819300, 2020). "Additionally, SFXN1 is functionally connected with key oncogenic regulators, positioning it as a central node in cancer-related molecular networks rather than a prognostic indicator." (PMID 41399448, 2026). "SFXN1 as well as SFXN2 and SFXN3 are regulated by the Myc transcription factor and may be involved in cancer cell growth in not yet investigated ways." (PMID 34350187, 2021).
kidney disease (1 paper, 2022). "Although PLPPR1 and SFXN1 genes have not been reported to be associated with kidney disease, the current study found that PLPPR1 and SFXN1 were significantly positively correlated with QDPR and negatively correlated with HAS2 and MYOF." (PMID 35320116, 2022).
neurodegenerative disease (1 paper, 2022). A disorder of the central nervous system characterized by gradual and progressive loss of neural tissue and neurologic function. "Since the steady-state levels of SFXN1 may be decreased in neurodegenerative diseases and its closest homologue SFXN3 may regulate synaptic morphology, we focused on candidate proteins that had been linked to neurological or neurodegenerative disorders." (PMID 36138777, 2022).
SFXN1 also shares sentences with these, for which no sentence is quoted: hepatocellular carcinoma (2 papers); Parkinson disease (2); acute myeloid leukemia (1); adrenocortical carcinoma (1); breast invasive carcinoma (1); lymphoma (1); mesothelioma (1); neurotoxicity (1).